CCL21 (C-C motif chemokine ligand 21)
Diseases named in the same sentence as CCL21 in open-access papers (continued):
Sharing a sentence is not in itself a finding about the gene and the disease.
atherosclerosis (continued). "A study by Guedj et al31 confirmed that the inflammatory factor CCL21 (C–C motif chemokine ligand 21) in human abdominal aortic aneurysms can trigger smooth muscle cells to produce chemokines, thereby aiding in the recruitment of immune cells and development of atherosclerosis." (PMID 34997174, 2022). "Considering the critical role of lymphatic EC-derived CCL21 in regulating the trafficking of APCs, and perhaps other adaptive immune cells, there is an impetus to determine the extent to which adventitial lymphatics are a viable target for atherosclerosis therapy." (PMID 32091396, 2020). "Increased CCL21 levels have been reported in atherosclerosis both systemically and within the lesion, but whether this represents a pathogenic inflammatory response or compensatory beneficial mechanisms leading to enhanced exit of leukocytes from the lesion is still unclear." (PMID 25398010, 2014). "We previously showed increased levels of CCL19 and CCL21 in coronary artery disease, and it may be argued that the raised levels of these mediators in HF merely reflect that several of these patients also have accompanying atherosclerosis." (PMID 22427939, 2012). "CCL2 and CCL5 are primarily involved in monocyte and SMC recruitment, promoting the formation of atherosclerosis, whereas CCL19 and CCL21 facilitate macrophage emigration, thereby promoting the regression of advanced plaques." (PMID 40236901, 2025). "In the MINOCA group, factors associated with atherosclerosis progression were concentrations of sVCAM-1 and CCL-21, while in the MI-CAD group, concentrations of CCL-8 and CXCL6 were the main determinants of atherosclerosis progression." (PMID 38138896, 2023). "The expression of CCR7 in macrophage is essential for decreasing the macrophage amount in plaques and promoting the regression of atherosclerosis, by interacting with its specific ligands CCL19 and CCL21." (PMID 34345249, 2021). "Most importantly, these activated VSMCs themselves produce high levels of CXCL13 and CCL21, thus promoting TLO formation in adventitia in atherosclerosis." (PMID 31921189, 2019). "In advanced atherosclerosis, activated LTo-like VSMCs highly expressed CXCL13 and CCL21 to induce ATLO neogenesis." (PMID 31921189, 2019). "In the present study, we observed that patients with CAS had significantly elevated serum levels of CX3CL1, CXCL12, CCL19, CCL21, CCL2, and CCL5 compared to control individuals, suggesting that these chemokines are intricately involved in the initiation and progression of atherosclerosis." (PMID 40236901, 2025). "Variations in pro-inflammatory biomarkers such as soluble vascular cell adhesion molecule-1 (sVCAM-1) and Chemokine (C-C motif) ligand 21 (CCL-21) in MINOCA patients suggest that plaque structure changes and microcirculatory alterations contribute to atherosclerosis progression." (PMID 39200755, 2024). "CCL21 and CCL19, chemokines involved in vascular inflammation and atherosclerosis, might be modulated by CARMN to regulate immune cell behavior affecting VSMCs." (PMID 38597937, 2024). "However further research is required in vivo to determine the CCL19/CCL21/CCR7 role in the recruitment and infiltration of monocytes in atherosclerosis and to determine its therapeutic potential." (PMID 33503867, 2021). "Furthermore, the CCL21 molecule and its receptor CCR7 have a possible role in the development of atherosclerosis by recruiting T cells and macrophages to the atherosclerotic lesions and by promoting inflammatory responses in these cells." (PMID 20461788, 2010). "Notably, these correlations might suggest a link between the metabolome and protein markers related to immune signalling (LTα, CD6, CCL21, SELE), energy balance and metabolism-related hormones (IGFBP1, SHGB, ADM, leptin, and STC1), and atherosclerosis/thrombosis inhibitor (PAI1)." (PMID 39154540, 2024).
rheumatoid arthritis (15 papers, 2007 to 2025). A chronic, systemic autoimmune disorder characterized by inflammation in the synovial membranes and articular surfaces. "Chemokine CCL21 activates microglia in the central nervous system and is expressed in neurons after an insult or mechanical injury, implicated in neuropathic pain, rheumatoid arthritis and pulmonary fibrosis." (PMID 34876093, 2021). "Lee and collaborators (2017) have shown that treatment with IL-1β and TNF-α raised CCR7 expression in both precursors and differentiated osteoclasts, increasing their migratory activity toward CCL19 and CCL21 chemokines upregulated in rheumatoid arthritis." (PMID 36831188, 2023). "The upregulation of CCL19 and CCL21 and their receptor CCR7 was associated to Rheumatoid arthritis pathogenesis, playing an important role in bone destruction by increasing osteoclast migration and resorption activity." (PMID 31888477, 2019). "CCL21 expression is upregulated in rheumatoid arthritis wherein CCL21 is the critical CCR7 ligand mediating migration, whereas CCL19 is redundant." (PMID 28474508, 2017). "Notably, a study in rheumatoid arthritis shows that CCL21/CCR7 signaling increases the number of macrophages in synovial tissue and promotes joint inflammation, making CCL21 an attractive target for therapy." (PMID 36211384, 2022). "Others have reported that CD197 (CCR7) mRNA levels in monocytes correlate to the clinical inflammation status (DAS28) in rheumatoid arthritis patients and that signaling of CD197 (CCR7) (by CCL21) promotes Th17-mediated bone loss an important destructive process in PsA." (PMID 34681660, 2021). "The factors driving TLS generation are complex; for example, fibroblasts in the tissues of rheumatoid arthritis produce lymphochemokines such as CXCL13, CCL19, and CCL21, which are involved in TLS formation." (PMID 40718780, 2025). "CXCL13, CCL21, and CXCL12, were also found in chronic inflammatory diseases, including SS, rheumatoid arthritis, and other disease models." (PMID 31921189, 2019). "The ligands CCL19 and CCL21, and their receptor CCR7 have been found to be involved in homing of lymphocytes to the target organ and to be localized in the lymphocytic infiltrates of the synovium in patients with rheumatoid arthritis." (PMID 17900348, 2007).
lymph node metastasis (14 papers, 2009 to 2024). "The CCL21/CCR7 axis has been associated with lymph node metastasis of several cancers, including breast (for review see:)." (PMID 23667660, 2013). "Previous studies have suggested that CCL21 is highly expressed in some solid cancers with lymph node metastasis." (PMID 27505247, 2016). "In addition, high expression of CCL21 was related to lymph node metastasis and poor prognosis in GC patients." (PMID 33602220, 2021). "Other cell adhesion molecular markers associated with lymph node metastasis, such as the chemokine receptors CCR7, CXCR3 and CCL21, could be related to distant metastasis development." (PMID 28705152, 2017). "Similarly, the downregulation of CCR7 in the bone-seeking variants could also be explained by its role and that of its ligands (CCL19 and CCL21) in lymph node metastasis." (PMID 35158871, 2022). "Other cell-adhesion-molecular markers associated to lymph-node metastasis, as chemokine receptors CCR7, CXCR3 and CCL21, could be related to brain metastasis development, thus, studies about analysis of their association with brain metastasis development are justified." (PMID 19386089, 2009). "Analysis of patient NSCLC tissue concluded that CCR7 and CCL21 levels correlated with VEGF-D expression, lymphatic vessel density, higher clinical stages, lymph node metastasis and decreased patient survival." (PMID 35203305, 2022). "Chemokine CCL21 and its unique receptor CCR7 had been described as vital factors determining cancer lymph node metastasis, and they were observed elevated in colorectal liver metastases." (PMID 33878734, 2021). "Consistent with former research, CCL21/CCR7 was highly expressed in cancer tissues, especially in patients with lymph node metastasis." (PMID 27505247, 2016). "Moreover, using monoclonal antibodies against CCL21 could prevent lymph node metastasis." (PMID 21548969, 2011). "Researchers hypothesize that the interaction between CCR7 and its corresponding ligand, CC chemokine ligand 21/secondary lymphoid tissue chemokine (CCL21/SLC), may be responsible for the occurrence of lymph node metastasis." (PMID 38225277, 2024). "Thus, mut-CCL21 was only assessed for its potential to prevent lymph node metastasis but not for its curative or prophylactic effect." (PMID 34298676, 2021).
gastric cancer (13 papers, 2019 to 2024). A primary or metastatic malignant neoplasm involving the stomach. "Meanwhile, a higher expression of CCL21 in stomach cancer tissues is closely related to lymph node metastasis, high incidence of tumor metastasis, and depth of gastric wall invasion." (PMID 34367971, 2021). "In gastric cancer, the high expression of CCR7 and CCL21 can lead to the preferential metastasis of gastric cancer cells to lymphatic vessels." (PMID 33158173, 2020). "CCL5, CCL22, CCL21, CCL2, and CCL15 were correlated with effector memory CD4 T cell in T1/T2 stage gastric cancer, and the number of cells was associated with the expression of IL3, IL17F, IL18, IL22, and IL31." (PMID 33426088, 2020). "In gastric cancer, high expression of CCL21 in tumor tissues was correlated with tumor invasion and lymph node metastasis." (PMID 31523177, 2019). "Moreover, CCL21-mediated activation of the MALAT1/SRSF1/mTOR axis underpins the development of gastric carcinoma." (PMID 34421979, 2021). "Therefore, correlation of CDK12 expression with CD8+ cell density in gastric cancer was investigated, as well as CC-chemokine ligand 21 (CCL21) expression, a chemokine which can induce T cell infiltration." (PMID 31523177, 2019). "From the results of present study, CCL21 could be one of the potential downstream effect genes of CDK12 in gastric cancer." (PMID 31523177, 2019). "In a mouse model of spontaneously developing gastric cancer by activated STAT3 signaling, chemokines CXCL13, CCL19, and CCL21 were induced simultaneously with tumorigenesis and TLS formation." (PMID 35552285, 2022). "CCL19 and CCL21 are chemokines and CCR7 is their receptor in gastric cancer and esophageal squamous cell carcinoma." (PMID 36263088, 2022). "CCL20/CCR6 induced gastric cancer EMT through the activation of the AKT pathway in response to CrkL; similar results were found with CCL21/CCR7 axis activated JAK2/STAT3 signaling pathways in promoting stemness of OSCC EMT progression." (PMID 34943853, 2021). "Positive correlations of CD8+ cell number and CCL21 mRNA expression with CDK12 were identified, which indicated the potential mechanisms of CDK12 regulating biological behavior of gastric cancer." (PMID 31523177, 2019). "CCL21 has been found to be overexpressed in patients with gastric cancer, and further studies have shown that it upregulates the expression of MALAT1, activates the mTOR signaling pathway, and promotes migration, invasion, and epithelial–mesenchymal transition (EMT) of gastric cancer cells." (PMID 39840050, 2024). "Therefore, further investigations should be performed to validate the hypothesis of CDK12/CCL21 pathway in regulation malignant function of tumor cells and immune microenvironment in gastric cancer, as well as the mechanisms of CDK12 regulating CCL21 expression." (PMID 31523177, 2019).
colorectal cancer (11 papers, 2016 to 2025). A primary or metastatic malignant neoplasm that affects the colon or rectum. "CCL21 has been reported to correlate with favorable prognosis in colorectal cancer and Ewing sarcoma." (PMID 37081973, 2023). "Several studies have shown that AKT mediated CCL21 induced upregulation of Snail confers stem cell properties and chemo-resistance in colorectal cancers, and multidrug resistance in MCF-7 cells." (PMID 33227065, 2020). "Furthermore, in tissue sections of liver tumors from patients with colorectal cancer liver metastases, the high expression of both CCR7 and CCL21 suggests that CCR7/CCL21 signaling promotes colorectal cancer liver metastasis." (PMID 40038879, 2025). "Yang showed that CCL21 can suppress the migration and invasion of colorectal cancer cell line." (PMID 34321013, 2021). "Our study suggested that CCL21 might lay the foundation for future development of CCL21-based therapies for colorectal cancer treatment." (PMID 27057280, 2016). "In our study, we found that CCL21 can upregulate the expression of P-glycoprotein (P-gp) and stem cell property markers such as Bmi-1, Nanog, and OCT-4 in colorectal cancer (CRC) HCT116 cells and then improve the cell survival rate and mammosphere formation." (PMID 27057280, 2016).
COVID-19 (11 papers, 2021 to 2025). A disease caused by infection with severe acute respiratory syndrome coronavirus 2. "High levels of CCL21 are associated with persisting pulmonary impairment post-COVID-19 hospital admission, and CCL21 is recognized for its involvement in recruiting CCR7+ T cells to secondary lymphoid organs, orchestrating the adaptive immune response." (PMID 38474155, 2024). "Here the authors spatially associate CCL18 and CCL21 in distinct tissue niches with lung pathology of severe COVID-19." (PMID 36774347, 2023). "In particular, CCL19 and CCL21 have been emphasized as markers of immune dysregulation in COVID-19, potentially indicating abnormal regulation induced by tissue inflammation." (PMID 40362649, 2025). "A small subset of genes involved in neutrophil and T cell activation (CXCL5, CXCL9, CCL21) were expressed in both COVID-19(+) TV and COVID-19(-) PU groups." (PMID 37026002, 2023). "Our results also demonstrate an enrichment in CCL21 in prolonged COVID-19, being spatially restricted to activated adventitial spaces with ongoing EndMT." (PMID 36774347, 2023). "C8 showed high expression of CCL21, a chemokine that was hardly detectable in acute COVID-19 samples, but highly upregulated in later disease phases." (PMID 36774347, 2023). "Interestingly, a recent study reported that 12 months after infection, patients with mild COVID-19 had higher autoantibody levels to cytokines such as CCL21, CXCL13, and CXCL16, compared to long COVID-19 patients." (PMID 38491326, 2024). "Thus, while T cell activation persists in the draining lymph nodes, CCL21-enriched lung adventitial niches in prolonged COVID-19 host T cell aggregates with an exhausted phenotype, suggesting local imprinting of the immune response." (PMID 36774347, 2023). "We identified upregulation of several NFκB pathway components (NFKB2 and NFKBIA) and inflammatory cytokines (CXCL9, CCL17, and CCL21) in the presence of viral transcripts, in line with the abundant literature describing these molecules in the early steps of COVID-19 pathogenesis." (PMID 37858234, 2023). "We show here that myofibroblasts in COVID-19 lungs also express CCR7 and, thus, can respond to the elevated CCL21 signals within the adventitial niches, particularly in the prolonged disease phase." (PMID 36774347, 2023). "In fact, patients with COVID-19 presented the upregulation of T cell markers, such as CD4, CCL21, CD48 and TNFRSF1B/TNFR2." (PMID 37047248, 2023). "The precise role of CCL21 in the activation and impairment of proper T cells during SARS-CoV-2 infection remains unclear; thus, a subsequent study may define the precise role of this chemokine post-SASR-CoV-2 infection." (PMID 35893822, 2022). "In addition, the serum levels of CCL21 were found to be high in patients with COVID-19 who did not survive 12 days after SARS-CoV-2 infection." (PMID 35893822, 2022).
autoimmune disease (10 papers, 2017 to 2025). A disorder resulting from loss of function or tissue destruction of an organ or multiple organs, arising from humoral or cellular immune responses of the individual to their own tissue constituents. "CCL21, a chemokine involved in the recruitment of T cells and dendritic cells to inflamed tissues, plays a crucial role in immune cell trafficking and has been implicated in the chronic inflammation characteristic of autoimmune diseases." (PMID 39767148, 2024). "In RA, another autoimmune disease with the formation of TLOs as HT, CCL21 was abundantly expressed in synovial tissues." (PMID 35140214, 2022). "Additionally, CCL21 enhances T cell infiltration and amplifies immune inflammation in Th1-type immune responses in various autoimmune diseases." (PMID 40160813, 2025). "It has been shown that the loss of CCL21 responsiveness in the normal development of the memory T-cell effector function does not hold for autoimmune diseases." (PMID 34456974, 2021). "According to the GWAS Catalog and Immunobase, five of these shared loci (PADI4 at 1p36.13, NAB1 at 2q32.3, COBL at 7p12.1, CCL21 at 9p13.3, and GATA3 at 10p14) have been associated with a single autoimmune disease so far and thus they represent new pleiotropic loci in autoimmunity." (PMID 30572963, 2018). "Similar to the CCL19/CCL21/CCR7 axis, the CCL20/CCR6 axis serves an essential role in the recruitment of inflammatory cells in the immune response and may contribute to a variety of autoimmune diseases, such as MS, IBD, psoriasis, and RA." (PMID 35702353, 2022).
non-small cell lung carcinoma (10 papers, 2008 to 2023). A group of at least three distinct histological types of lung cancer, including non-small cell squamous cell carcinoma, adenocarcinoma, and large cell carcinoma. "When combined with the CCL21 chemokine, which recruits T cells and enhances T-cell responses, additive effects have been demonstrated in non-small cell lung cancer mouse models." (PMID 30209589, 2018). "Intratumoral administration of clinical grade CCL21-transduced DC will be evaluated in a phase I clinical trial for late stage Non-Small Cell Lung Cancer." (PMID 18644162, 2008). "Strikingly, systemic TAA-specific immune responses and enhanced tumor CD8+ T-cell infiltration were even observed upon intra-tumoral injection of DCs containing an vector expressing the CCL21 gene in 16 patients with advanced non-small cell lung carcinoma (NSCLC)." (PMID 30559743, 2018). "Based on extensive pre-clinical evaluation, we began an NCI funded clinical trial one year ago assessing the intratumoral injection of DC transduced with an adenoviral vector expressing the CCL21 gene (Ad-CCL21-DC) in a phase I trial in advanced non-small cell lung cancer (NSCLC)." (PMID 21559281, 2011). "Based on our preclinical findings, we are assessing the efficacy of intratumoral injection of dendritic cells (DC) transduced with an adenoviral vector expressing the secondary lymphoid chemokine (CCL21) gene (Ad-CCL21-DC) in a phase I trial in advanced non-small cell lung cancer (NSCLC)." (PMID 21559281, 2011).